HAS3 (hyaluronan synthase 3)
Diseases named in the same sentence as HAS3 in open-access papers (continued):
Sharing a sentence is not in itself a finding about the gene and the disease.
tumor (continued). "Notably, the analysis of HAS3, ABCC5, SOX2 and CD133 tumor mRNA transcripts showed that Pa + 4Mu combination therapy significantly downregulated gene expression, as was observed in the previous in vitro assays (p < 0.01)." (PMID 39039104, 2024). "Following HA degradation, their effects would no longer be attenuated, resulting in the increase in 4T1/HAS3 tumour MTR measured herein." (PMID 37081807, 2023). "A CD44v6kd tumor line secretes a matrix that does not support adhesion of CD44vwt or CD44v6kd cells, the CD44v6kd cells displaying reduced HA synthase 3 (HAS3) expression, but abundantly secrete hyaluronidase (Hyal)." (PMID 27419629, 2016). "HAS3 immunostainings did not correlate with the histological type of specimens, or with tumor grade." (PMID 19435493, 2009). "However, while the treatment abrogated mRCC in mice implanted with EV-luc cells, it failed to do so in HAS3-luc tumor-bearing mice." (PMID 36581895, 2022). "Interestingly, EGF‐R expression has been positively correlated with that of HAS3 in human oesophageal SCC tumours and activation of EGF‐R enhances HAS3 expression in some tumour cells, implying a positive feedback between EGF‐R signalling and ∆Np63‐HAS3 pathway in HNSCC." (PMID 30845357, 2019). "In addition, the relative importance of stromal versus tumour cell HAS expression has not been addressed experimentally in any cancer yet, which is due to the fact that HAS2 deficient mice are lethal and HAS1 and HAS3 deficient mice are not available to the scientific community." (PMID 21429221, 2011). "Interestingly, in our system, significantly increased expression of synthases (HAS2, HAS3) and hyaluronidases (HYAL1, HYAL3, HYAL4) was detected in the tumor cells but not in the stromal portion of TW2.6 tumors." (PMID 34869001, 2021). "When comparing TT and NAT, we noticed a high variability of HAS2, HAS3 and HYAL2 among the patients for both tumor types while HAS1 and HYAL3 could not be detected." (PMID 32610620, 2020).
cancer (44 papers, 2009 to 2025). A tumor composed of atypical neoplastic, often pleomorphic cells that invade other tissues. "Further studies employing CRISPR knockdown of HAS3 (and other top genes) are needed to further explore the significance of these novel mechanisms and their impact on cancer stemness and its association with METRO-TOPO treatment-related efficacy." (PMID 37476073, 2023). "The HAS3 protein significantly induced N2a cancer cell differentiation and caused autophagic cell death." (PMID 34770956, 2021). "HAS3, and particularly its product hyaluronan (HA), are carried by EVs and are known to be associated with the tumorigenic properties of cancer cells." (PMID 31820036, 2020). "Furthermore, a significant association between high CD44, HAS2 and HAS3 mRNA levels and a cancer-cell pericellular HA-deposition pattern was noted." (PMID 36428513, 2022). "HAS3 (hyaluronan synthase 3) is also strongly implicated in cancer development." (PMID 30069008, 2018). "Increased levels of LMWHA in malignant tumors suggest that HAS3, CEMIP, and CEMIP2 function as key enzymes." (PMID 39858106, 2025). "The study comprehensively describes the characteristics of HAS1, HAS2, and HAS3 in cancers using public databases and tools, to identify the potential biological pathways involved at the molecular, protein, cellular, and clinical sample levels." (PMID 37636435, 2023). "HAS3 overexpression in cancer cells promoted a series of apoptotic processes, including membrane blebbing (denoted as step-1), the formation of apoptotic membrane protrusions (indicated as step-2), and cell fragmentation (marked as step-3)." (PMID 34770956, 2021). "In this study, low serum concentration (<0.5% FBS for 24 h) significantly induced HAS3 protein expression in MDA-MB-231 cancer cells." (PMID 34770956, 2021). "Time-dependent experiments demonstrated that treatment with 0.1% FBS as early as 12 h significantly induced HAS3 protein expression in cancer cells." (PMID 34770956, 2021). "We show quantitative analysis of filopodia in three human cancer cell lines with induced expression of HAS3, CD44, and variable hyaluronan synthase activity by manipulating the levels of sugar precursors for hyaluronan building blocks." (PMID 32679746, 2020). "The same effect on HAS2 expression was described in cancer cells in which the level of HAS3 mRNA was also reduced except for 1 cell line with very low HAS3 expression level." (PMID 32084270, 2020). "HAS3-EVs increased the expression of c-Myc, an oncogenic factor activated in many different cancers types." (PMID 31820036, 2020). "qRT-PCR performed to validate the microarray results showed that expression of a number of cancer-related genes, including HAS3, CD44, TP63, and SMYD2, was decreased by siRNAs targeting DLEU1, while expression of CDH1 was increased by DLEU1 knockdown." (PMID 30069008, 2018). "HAS1 mRNA were overexpressed in effusions, in contrast to primary carcinomas and solid metastases, whilst HAS2 mRNA was overexpressed in solid metastases and primary carcinomas compared to effusions and HAS3 mRNA was overexpressed in all subtypes." (PMID 29510526, 2018). "The inter-regulation of HAS3 and cytokines adds another layer of complexity in reglating HAS3 expression in cancer." (PMID 28107185, 2017). "HAS2 mRNA was overexpressed in solid metastases and primary carcinomas compared to effusions (p = 0.043), and HAS3 mRNA was overexpressed in primary carcinomas and effusions compared to solid metastases (p = 0.008)." (PMID 23202930, 2012). "We also noticed that HAS3 expression was also elevated (1.5-fold increase) in grade 1 malignant tumors compared to normal endometrium, this finding being borderline significant (p = 0.033)." (PMID 20875124, 2010).
cancer (continued). "The isoenzyme HAS3 shows a very important correlation with several cancer types, but the information about its regulation is still insufficient; nevertheless, the possibility that HAS3 could be linked to the release of EVs is a promising new target to explore." (PMID 36765756, 2023). "The variant rs2232228 in the HAS3 gene, which is believed to reduce the ability of HAS3 to synthesize hyaluronan, was identified to be associated with an ~9-fold increased risk of developing AIC in a cohort of pediatric cancer survivors." (PMID 35965684, 2022). "However, the specific features of HAS3-induced EVs and their role in cancer progression have yet to be studied." (PMID 31820036, 2020). "HAS expression patterns may be somewhat cancer specific; for example, metastatic prostate and colon cancer express higher levels of HAS3 than HAS2." (PMID 25852691, 2015). "Mammalian genomes have three different HAS genes (HAS1, HAS2, and HAS3) which are expressed at specific stages and in specific tissues during organ development, aging, wound healing, as well as under normal or pathologic conditions, including diseases such as cancer." (PMID 39766274, 2024). "Total RNA-seq showed upregulation of 12 putative cancer-related genes near ISs, including MAGI1-AS1, HAS3, CASC8, BIRC2, and MMP12." (PMID 41157614, 2025). "Some types of cancer cells express hyaluronan synthases (HAS1, HAS2, and HAS3), as well as embryonic cells, and HAS2-CD44 signaling is considered to play a vital role in malignant progression." (PMID 37064130, 2023). "High expression of hyaluronan synthase 3 (HAS3) resulted in HA deposition, which promoted the growth of cancer cell." (PMID 37476195, 2023). "In this study, a pan-cancer analysis of the three enzymes called hyaluronan synthases (HAS1, HAS2, and HAS3) that produce HA was performed." (PMID 37636435, 2023). "In a preclinical model of cancer, the MH194 PC cell line was transfected with hyaluronan synthase-3 (HAS3) to generate a syngeneic PC mouse model with high levels of HA." (PMID 35139879, 2022). "Microarray analysis revealed that DLEU1 knockdown significantly affects expression of a number of cancer-related genes in OSCC cells, including HAS3, CD44, and TP63, suggesting that DLEU1 regulates HA-CD44 signaling." (PMID 30069008, 2018). "Among three isoenzymes, HAS2 and HAS3 have been shown to produce extracellular HA, whereas HA synthesized by HAS1 has been identified in both intra- and extracellular compartments of cancer cells." (PMID 29137675, 2017). "Aggressive BC cells express high levels of HA synthase 2 (HAS2) and lower levels of HA synthase 3 (HAS3) compared to non-aggressive cancer cells." (PMID 40443562, 2025). "HAS3 is the most active enzyme of the HAS family and polymerizes shorter HA chains that stimulates cell signaling, proliferation, and epithelial-to-mesenchymal transition in cancer models." (PMID 32982773, 2020). "Most of the studies that correlate overexpressed HA in cancer have been focused on HAS2 and HAS3." (PMID 29137675, 2017). "IL-4 triggered expression of hyaluronan synthase 3 (HAS3) may facilitate the adhesion and migration of activated immune cells and cancer cells during inflammatory response and cancer metastasis, respectively." (PMID 27214384, 2016). "lncRNA-H19 and circular MYLK as well as circular CTDP1 could regulate the expression of DNMT3B, HAS3, VEGFA and ITGB1 through competing miRNA response elements (MREs) of miRNA-29a-3p, which would result in growth and metastasis of cancer." (PMID 27363013, 2016). "A dose-dependent reduction in the mRNA levels of HAS2 or HAS3 was observed in all the cancer cell lines examined, which is not consistent with the findings of the current study, in which Has1 and Has3 mRNA levels increased after treatment with MU." (PMID 22045192, 2011). "Normal specimens showed no HAS3 signal but 46% of the cancers presented generally low numbers of HAS3-positive cancer epithelial cells." (PMID 19435493, 2009).
cancer (continued). "There was little HAS1 mRNA, no consistent upregulation of HAS2 in the cancers, and the median values of HAS3 mRNA were actually lower in cancers than controls." (PMID 19435493, 2009). "As compared with normal ovaries, the median values of HAS3 in borderline and grade 1+2 malignant tumors were not changed, while grade 3 showed a trend for decline (-44%)." (PMID 19435493, 2009). "Finally, we found major differences among the cancer cell lines in their expression of genes involved in glycosylation, including CHST11, CHST13, Ext1, HAS2 and HAS3, which may have an impact on the architectural organization of the spheroids." (PMID 39011470, 2024). "Most of the previous studies on HA synthesized by HAS2 and HAS3 were focused mainly on its roles in the ECM and signal transduction, whereas the majority of HAS1 research has focused on prognostic marker studies or expression profiles of HAS1 genes in different cancers." (PMID 29137675, 2017). "The levels of HAS2 and HAS3 mRNA (HAS1 was low or absent), were not consistently increased in the carcinomas, and were not significantly correlated with HAS protein or hyaluronan accumulation in individual samples." (PMID 19435493, 2009). "However, the relationship between HAS3 and TNF-α expression has never been examined in human cancer patients." (PMID 28107185, 2017).
infection (2 papers, 2009 to 2024). The state of being infected such as from the introduction of a foreign agent such as serum, vaccine, antigenic substance or organism. "We demonstrated before that hyaluronan is the major attachment site of both BCG and M. tuberculosis in the infection of A549 cells, which itself produced hyaluronan probably depending on HAS3 and HAS2." (PMID 19876387, 2009). "Total RNA was extracted from the lungs after 1, 3, 5, 7, 14, and 21 days of infection, and analyzed for HAS1, HAS2, and HAS3 mRNA transcription by reverse transcriptase-polymerase chain reaction (RT-PCR)." (PMID 19876387, 2009). "To see if hyaluronan is present at the site of infection of M. tuberculosis, we assessed the expression of hyaluronan synthases (HAS1, HAS2, and HAS3) in the lungs of BALB/c mice infected with the M. tuberculosis H37Rv strain, using the low-dose aerosol infection model." (PMID 19876387, 2009).
adenocarcinoma (1 paper, 2022). A common cancer characterized by the presence of malignant glandular cells. "Our assumption that HA can be confirmed by the data that the dense arrays of HA chains, tethered to HAS3 during biosynthesis, can induce and maintain prominent microvilli in adenocarcinoma cells transfected with HAS3." (PMID 35203523, 2022).
benign tumors (1 paper, 2009). "Groupwise testing showed increased HAS3 expression in benign tumors compared to normal ovaries (median +60%, P = 0.0039)." (PMID 19435493, 2009).
intestine disease (1 paper, 2016). "HA synthesis mediated by HAS3 promotes inflammation and is pathogenic in animal models of human lung and intestinal disease." (PMID 27042213, 2016). "Consistently, published studies using animal models of human lung and intestine disease show that HA synthesized by HAS3 contributes to inflammation." (PMID 27042213, 2016).
liver (1 paper, 2016). "Therefore, HAS3-mediated HA production is pathologic in chronic liver injury." (PMID 27042213, 2016).
HAS3 also shares sentences with these, for which no sentence is quoted: osteosarcoma (3 papers); abdominal aortic aneurysm (1); adenomyosis (1); asthma (1); astrocytoma (1); bone tumors (1); breast adenocarcinoma (1); cardiac hypertrophy (1); cardiovascular disease (1); chondrosarcoma (1); COVID-19 (1); ductal carcinoma in situ (1); endothelial dysfunction (1); esophageal carcinoma (1); hepatocellular carcinoma (1); high-grade glioma (1); inflammation (1); kidney stones (1); lung adenocarcinoma (1); lung squamous cell carcinoma (1); metastatic colorectal cancer (1); metastatic melanoma (1); ovarian clear cell cancer (1); ovarian tumors (1); paraganglioma (1); pheochromocytoma (1); pleural mesothelioma (1); rheumatoid arthritis (1); sarcoma (1); skin disorder (1).
A further 3 diseases each share a sentence with HAS3 in 1 paper.